P4HA1 (prolyl 4-hydroxylase subunit alpha 1)
Description:
Catalyzes the post-translational formation of 4-hydroxyproline in -Xaa-Pro-Gly-sequences in collagens and other proteins.
Synonyms: P4HA; C-P4Halpha(I)
Tractability: Small molecule: a high-quality ligand is known. Antibody: UniProt predicts a signal peptide or a membrane-spanning region. PROTAC: ubiquitination databases record sites on it; its protein half-life has been measured; a small molecule that binds it is known.
Target class: Enzyme; Oxidoreductase
Gene: Protein-coding gene on chromosome 10 (73,005,811 to 73,096,983, reverse strand). Ensembl gene ENSG00000122884.
Subcellular location: Endoplasmic reticulum lumen
Subcellular location (Human Protein Atlas): Endoplasmic reticulum; Mitochondria; Vesicles
Pathways (Reactome):
Disease: Maturation of DENV proteins
Extracellular matrix organization: Collagen biosynthesis and modifying enzymes
Gene Ontology:
Molecular function: identical protein binding; procollagen-proline 4-dioxygenase activity; protein binding; iron ion binding; L-ascorbic acid binding; oxidoreductase activity, acting on paired donors, with incorporation or reduction of molecular oxygen
Biological process: collagen fibril organization
Cellular component: endoplasmic reticulum; membrane; endoplasmic reticulum lumen; procollagen-proline 4-dioxygenase complex
Genetic constraint (gnomAD): Loss-of-function variants: 2 observed, 14.68 expected, observed/expected ratio (o/e) 0.14, 90% interval 0.055 to 0.43. The upper end of that interval is the gene's LOEUF score, 0.43, which puts it in group 1 of 6, group 1 being the genes least tolerant of losing a copy. Missense variants: 135 observed, 187.66 expected, observed/expected ratio (o/e) 0.72, 90% interval 0.62 to 0.83. Synonymous variants: 72 observed, 71 expected, observed/expected ratio (o/e) 1.01, 90% interval 0.84 to 1.23.
Homologues: Orthologues: macaque P4HA1 (99% identical), dog P4HA1 (98% identical), pig P4HA1 (96% identical), rabbit P4HA1 (96% identical), rat P4ha1 (96% identical), mouse P4ha1 (95% identical), guinea pig P4HA1 (95% identical), chimpanzee P4HA1 (94% identical), tropical clawed frog p4ha1 (80% identical), zebrafish p4ha1b (73% identical), Drosophila melanogaster CG31021 (22% identical), Caenorhabditis elegans phy-3 (13% identical), and 2 more. Paralogues in human: P4HA2 (59% identical), P4HA3 (36% identical), P4HTM (18% identical).
Diseases named in the same sentence as P4HA1 in open-access papers:
P4HA1 is named in the same sentence as 104 diseases in open-access papers, as found by Europe PMC text mining. Sharing a sentence is not in itself a finding about the gene and the disease. The quoted sentences say what the papers report.
breast carcinoma (44 papers, 2014 to 2025). "Previous studies have shown that increased P4HA1 expression is associated with poor prognosis in some solid cancers, such as pancreatic cancer, colon cancer, high-grade glioma, breast cancer, prostate cancer, and lung cancer." (PMID 39568592, 2024). "Logistic regression analysis of associations between P4HA1 expression and the clinicopathologic variants of breast cancer." (PMID 33692831, 2021). "The expression of P4HA1 was significantly associated with the ER status group of breast cancer (OR = 0.38; 95% CI: 0.79–0.80, P = 0.011) but less significantly associated with the PR status group cancer (OR = 1.47; 95% CI: 0.71–3.03, P = 0.29)." (PMID 33692831, 2021). "We assessed the association of P4HA1 expression with breast cancer grade through combing grade 1 and grade 2 vs. grade 3 and results revealed no significance associated with grades (OR = 1.40; 95% CI: 0.76–2.57, P = 0.27)." (PMID 33692831, 2021). "Univariate and multivariate analysis of clinicopathological factors associated with the prognostic significance of P4HA1 expression in breast cancer." (PMID 33692831, 2021). "Its mRNA expression is also reported to associate with poor survival in breast cancer and squamous cell carcinoma, and the P4HA1 protein expression correlates with poor prognosis in high‐grade gliomas." (PMID 32053263, 2020). "We showed that increased P4HA1 expression in primary tumors was associated with a short distant metastasis-free survival in breast cancer patients." (PMID 30367042, 2018). "The upregulation of P4HA1 in breast cancer cell lines is associated with increased secretion of collagen." (PMID 30367042, 2018). "Given that the loss of P4HA1 may disrupt stem cell development and inflammation response, our results suggest that targeting P4HA1 may offer a promising therapeutic strategy for breast cancer treatment." (PMID 40694594, 2025). "In addition, this analysis also revealed a strong association of P4HA1 gene expression with the ER of breast cancer." (PMID 33692831, 2021). "According to existing research, the role of P4HA1 in pancreatic cancer, colon cancer, high-grade glioma, breast cancer, prostate cancer, lung cancer and other cancers has been preliminarily verified." (PMID 39568592, 2024). "P4HA1 has an important role in the HIF-1 signaling pathway and is associated with various tumors, namely HNSCC, breast cancer, colorectal cancer, and B-cell lymphoma." (PMID 37796226, 2023). "In breast cancer, P4HA1 can regulate HIF-1α expression via regulating α-KG and succinate levels, which promotes chemoresistance by regulating the HIF-1–dependent cancer cell stemness." (PMID 35812752, 2022). "The total protein level of P4HA1 was increased in breast cancer, OV, colon cancer, clear cell RCC, UCEC, and LUAD in the CPTAC dataset." (PMID 35812752, 2022). "We also used the CPTAC database to evaluate the total protein level of P4HA1 in breast cancer, OV, colon cancer, clear cell RCC, UCEC, and LUAD." (PMID 35812752, 2022). "The P4HA1 or P4HA2 knockdown also prevented breast cancer metastasis in mice by inhibiting collagen fiber development, thereby making it challenging for tumor cells to migrate into surrounding tissue." (PMID 36140753, 2022). "We discovered positive correlations between the high P4HA1 expression and poor OS, distant metastasis-free survival, and relapse-free survival in breast cancer, poor OS and PFS in ovarian cancer, and poor OS in lung cancer." (PMID 35812752, 2022). "The results demonstrated that P4HA1 was upregulated in brain and CNS cancer, breast cancer, CRC, head and neck cancer, kidney cancer, lung cancer, pancreatic cancer, and SARC compared with the normal tissues." (PMID 35812752, 2022). "Our findings revealed that P4HA1 gene expression is reliably expressed in breast cancer vs. normal cells." (PMID 33692831, 2021).
breast carcinoma (continued). "It was reported that HIF-1 promotes P4HA1 expression to induce collagen deposition and a more aggressive phenotype in human breast cancer, leading to poor prognosis for breast cancer patients." (PMID 33941139, 2021). "This research extensively examined the expression of P4HA1 in breast cancer cells and its therapeutic relevance in tumor-affected samples using integrative functional multi-omic approaches." (PMID 33692831, 2021). "P4HA1 knockdown has been shown to reduce tumor density and stiffness also in breast cancer xenografts." (PMID 32053263, 2020). "This has also been described for breast cancer xenograft tumors, where P4HA1 silencing inhibits tumor invasion and formation of lung and lymph node metastases." (PMID 32053263, 2020). "In breast cancer, upregulated P4HA1 was crucial for HIF-1α stabilization, cancer metastasis, and chemoresistance." (PMID 33299876, 2020). "It was reported that P4HA1 is dysregulated in many cancers; for example, it promotes breast cancer drug resistance, and plays an important role in the differentiation of glioma stem cells." (PMID 32436609, 2020). "Previous evidence indicated that elevated P4HA1 expression was related to poor prognosis in some solid cancers, such as pancreatic cancer, head and neck cancer, high-grade gliomas, breast cancer, prostate cancer, and oral cancer." (PMID 33299876, 2020). "Recently, P4HA1 was shown to play an essential role in breast cancer tumorigenesis and distant metastases by stabilizing HIF-1α via reducing its proline hydroxylation, resulting in escape from degradation." (PMID 32166002, 2020). "Previously, the increased P4HA1 expression correlates with poor prognosis has been demonstrated in several cancers, including breast cancer, oral squamous cell carcinoma, melanoma, and prostate cancer." (PMID 32635458, 2020). "Tissue microarray data showed that P4HA1 protein expression is significantly upregulated in TNBC compared to ER positive breast cancer." (PMID 31225497, 2019). "Nevertheless, the fact that P4HA1 expression correlates with HIF-1 activation in breast cancer tissues suggests that hyperactivation of HIF-1α in TNBC is at least partially induced by P4HA1." (PMID 30367042, 2018). "Quantitative RT-PCR data showed that silencing P4HA1 in breast cancer cells significantly reduced mRNA levels of LDHA and PDK1 under normoxia and hypoxia conditions." (PMID 30367042, 2018). "We also found that silence of P4HA1 reduced ECAR in breast cancer cells, and HIF-1α PPAA mutant restored ECAR in P4HA1-silenced cells." (PMID 30367042, 2018). "In the present study, we show that the major role for collagen hydroxylation enzyme P4HA1 in breast cancer cells is to enhance HIF-1 protein stability by reducing availability of α-KG and by producing succinate." (PMID 30367042, 2018). "Treatment with dimethyl-succinate slightly increased HIF-1α protein levels in P4HA1-silenced breast cancer cells." (PMID 30367042, 2018). "To define the roles of P4HA1 in breast cancer progression, we analyzed P4HA1 protein levels in human breast cancer tissue using tissue microarrays generated at UKY." (PMID 30367042, 2018). "In fact, silencing P4HA1 significantly reduced succinate levels in the cytoplasm of breast cancer cells." (PMID 30367042, 2018). "Expression of the HIF-1 gene signature was significantly correlated with P4HA1 levels in human breast cancer tissue." (PMID 30367042, 2018). "We found that P4HA1 expression inhibited oxidative phosphorylation and reduced ROS levels in breast cancer cells." (PMID 30367042, 2018). "The knockdown of either HIF-1α, P4HA1, or P4HA2 decreases tumor fibrosis and P4HA1 or P4HA2 knockdown completely abrogates the spontaneous metastasis of mammary fat pad-implanted human breast cancer cells to the lungs and lymph nodes of immunodeficient mice." (PMID 27706047, 2016).
breast carcinoma (continued). "Given the roles of inflammation in cancer development, our results indicate that inhibiting P4HA1 could offer a promising therapeutic strategy for treating breast cancer." (PMID 40694594, 2025). "Thus, the P4HA1 9a isoform is increased under hypoxic conditions and renders the breast cancer cells more invasive by providing a more invasion conducive ECM." (PMID 40016181, 2025). "Finally, to assess the functional importance of the P4HA1 9a isoform and its role in hypoxia-mediated invasion of breast cancer cells, we overexpressed the two isoforms in wild type normoxic cells and P4HA1 knockdown hypoxic cells." (PMID 40016181, 2025). "However, only several researches have stated the role of P4HA1 in tumor diseases, and most of them are breast cancer related 24-27." (PMID 34659558, 2021). "P4HA1 also could increase the occurrence of tumor proliferation, invasion, metastasis and chemoresistance in mammary cancers 8-10." (PMID 34659558, 2021). "However, increasing evidence shows that P4HA1 is related to the occurrence, invasion, and metastasis of some human cancers including breast cancer and prostate cancer, glioma, and hepatocellular carcinoma." (PMID 33415167, 2020). "In breast cancer, high P4HA1 and P4HA2 mRNA levels in primary tumors associate with poorer overall survival, and knockdown of either P4HA1 or P4HA2 may reduce collagen deposition and inhibit tumor invasion and metastasis in vivo." (PMID 32053263, 2020). "In addition, in a human protein atlas database for normal and cancer tissues, high P4HA1 mRNA expression showed poorer prognosis in renal, head and neck, cervical, pancreatic, lung, and breast cancers." (PMID 32166002, 2020). "Interestingly, induction of P4HA1 expression in cancer cells is required for breast cancer metastasis." (PMID 30367042, 2018). "Importantly, treatment with the proteasome inhibitor Bortezomib rescued HIF-1α protein expression in P4HA1-silenced breast cancer cells." (PMID 30367042, 2018). "It is plausible that P4HA1 expression is regulated by EMT drivers during breast cancer progression." (PMID 30367042, 2018). "P4HA1 expression is induced during breast cancer development and TNBC progression." (PMID 30367042, 2018). "Inhibition of the P4HA1/HIF-1 axis suppresses stemness in breast cancer cells." (PMID 30367042, 2018). "In human breast cancers, P4HA1 is overexpressed and correlated with patient prognosis." (PMID 28415787, 2017). "Importantly, P4HA1 expression in cancer cells is required for breast cancer metastasis." (PMID 31225497, 2019). "Recent studies have highlighted the role of P4HA1 in promoting tumor growth and metastasis across various cancer types, such as the P4HA1/HIF1 pathway, which is essential for the stemness of breast cancer cells." (PMID 41469036, 2025). "Together, these results agree with our previous study showing that P4HA1 regulates ROS and oxidative phosphorylation via the HIF-1 pathway in breast cancer cells." (PMID 40694594, 2025). "Inhibition of HIF-1α, P4HA1, or P4HA2 via short hairpin RNAs has been shown to decrease collagen deposition in breast cancer cells and fibroblasts in vitro." (PMID 36140753, 2022). "P4ha1, only regulated in short-term hypoxia, is known to induce HIF-1 signaling in breast cancer cells through hypoxia." (PMID 36411871, 2022). "Increased mRNA levels of P4HA1 and P4HA2 have been observed in human breast cancer facilitating collagen deposition and further promoting invasion and metastasis." (PMID 35202840, 2022). "A recent study suggests that P4HA1 is essential for HIF-1 protein stability and is a new regulator of the HIF-1 pathway in breast cancer cells." (PMID 32635458, 2020). "The overexpression of P4HA1 in cancer cells increases LDHA mRNA levels, and P4HA1 expression correlates with LDHA mRNA levels in human breast cancer tissue, which are consistent with our finding." (PMID 32635458, 2020).
breast carcinoma (continued). "We found that P4HA1 expression reduced oxidative phosphorylation and induced HIF-1-targeted gene expression in breast cancer cells." (PMID 30367042, 2018). "Here, we show that P4H alpha 1 subunit (P4HA1) protein expression is induced in triple-negative breast cancer (TNBC) and HER2 positive breast cancer." (PMID 30367042, 2018). "We showed that P4HA1 expression was upregulated in TNBC and HER2-positive breast cancer tissues compared to the ER-positive breast cancer." (PMID 30367042, 2018). "Silencing HIF-1α blocks the expression of P4HA in vitro, and knockdown of P4HA1 inhibits tumor growth and metastasis in breast cancer in vivo." (PMID 28415787, 2017). "P4HA1 and P4HA2 in the cancer cells have been shown to be critical for breast cancer cell line collagen deposition, invasion and metastasization." (PMID 27809802, 2016). "In particular, upregulation of the P4HA1 in breast cancer cells increased HIF-1 protein stability, accompanied by decreased respiration, glycolysis, oxidative phosphorylation, and reactive oxygen species (ROS) levels in breast cancer cells." (PMID 40694594, 2025). "In sum, hypoxia directly regulates ECM composition via multiple enzymes and, as such, P4HA1, P4HA2, PLOD2, and LOX enzymes could be used as biomarkers in breast cancer progression." (PMID 36140753, 2022). "Additionally, in vivo experiments confirm this observation by proving that inhibiting HIF-1α, P4HA1, or P4HA2 in orthotopic tumors, developed via injection of human breast cancer cells into immunodeficient mice, decreases tissue stiffness and fibrosis." (PMID 36140753, 2022). "The Violin Plot revealed the difference between with and without hypoxic exposure in breast cancer cells in the mRNA expression of P4HA1." (PMID 33692831, 2021). "P4HA1 and P4HA2 expression has been reported to be altered in diverse tumor types, including oral cavity squamous cell carcinoma, prostate cancer, hepatoma, and breast cancer, and involved in tumor progression." (PMID 34168290, 2021). "HIF-1 promotes extracellular matrix remodeling by inducing P4HA1 and P4HA2 in breast cancer." (PMID 31467922, 2019). "In addition, P4HA1 expression significantly correlated with mRNA levels of LDHA and PDK1 in human breast cancer tissue." (PMID 30367042, 2018). "Also, α-KG consumption by P4HA1 may regulate a HIF-1-dependent tumor stemness and drug resistance in breast cancer cells." (PMID 38907027, 2024). "However, the unbiased gene co-expression analysis did not detect the association between P4HA1 and the STAT3 pathway or gene signature in human breast cancer tissues." (PMID 30367042, 2018). "Furthermore, neither ECM metagene-adjusted P4HA1 nor P4HA2 levels were higher in breast cancer than in normal tissue, which also contrasts what was found for P4HA3." (PMID 27809802, 2016). "Notably, CDK1, CCNA2, P4HA1, PAICS, and RAD51 showed a CERES score higher than zero in most breast cancer cell lines, indicating that they might not be essential to breast cancer." (PMID 34745136, 2021).